TACC3 (transforming acidic coiled-coil containing protein 3)
Diseases named in the same sentence as TACC3 in open-access papers (continued):
Sharing a sentence is not in itself a finding about the gene and the disease.
tumor (continued). "To surmise, this research discovered that the expression of TACC3 could influence the constituent proportion of NK cells and T cells in the immune microenvironment of LUAD tumor tissues, thus incidentally influencing tumor progression and controlling immune surveillance." (PMID 35855850, 2022). "While it is unclear if the role of TACC3 in regulating the epithelial-mesenchymal transition may relate to the methylation characteristics of F3T3-positive GBM, it has been suggested that methylation subclass is reflective of tumor cell of origin as well as somatic epigenetic changes." (PMID 33168106, 2020). "However, TACC3 was also expressed in many non-mitotic tumor cells on IHC." (PMID 29135996, 2017). "MSI analysis revealed significant positive correlations for TACC3 and CXCL1 (p < 0.05), suggesting their potential roles in MSI-high tumor biology, whereas ABCB1, TGFBI, and VDR lacked significant associations with MSI status." (PMID 40791849, 2025). "TACC3 protein expression (92.2%, 12/13) was increased in the HCC tumor tissues compared with the non-cancerous samples." (PMID 26219398, 2015).
adenocarcinoma (6 papers, 2016 to 2025). A common cancer characterized by the presence of malignant glandular cells. "Additionally, 320 patients with adenocarcinoma from TCGA database were included in the survival analysis and categorized into the TACC3 high-expression group (n = 168) and low-expression group (n = 152) using a cutoff value of 2.7625." (PMID 39603208, 2025).
infection (2 papers, 2023). The state of being infected such as from the introduction of a foreign agent such as serum, vaccine, antigenic substance or organism. "Immunofluorescence (IF) staining results showed that infection with the TACC3 shRNA lentivirus effectively reduced TACC3 protein expression in Panc-1 cells." (PMID 38012214, 2023). "First, we overexpressed 3×Flag-TACC3 in Panc-1 cells via lentiviral infection and measured the expression level of KIF11 by Western blotting." (PMID 38012214, 2023).
digestive system cancer (1 paper, 2017). A primary or metastatic malignant neoplasm involving any part of the digestive system. "In the stratified analysis for OS, patients with high levels of TACC3 may act as a reliable prognostic marker in digestive system cancers, which was concordant with our conclusion." (PMID 29088887, 2017).
TACC3 also shares sentences with these, for which no sentence is quoted: cholangiocarcinoma (6 papers); osteosarcoma (5); head and neck squamous cell carcinoma (4); liver cancer (4); oligodendroglioma (4); squamous cell lung carcinoma (4); urothelial bladder carcinoma (4); diffuse astrocytoma (3); invasive ductal carcinoma (3); neuroblastoma (3); Neuroepithelial Tumor (3); bladder tumor (2); ductal carcinoma in situ (2); gallbladder cancer (2); lung (2); lymph node metastases (2); lymphoma (2); oral cancer (2); small cell lung carcinoma (2); stomach cancer (2); acute promyelocytic leukemia (1); adrenal carcinoma (1); anal carcinoma (1); anaplastic astrocytoma (1); astrocytomas (1); autoimmune thyroid disease (1); benign breast tumors (1); brain cancer (1); brain tumors (1); breast adenocarcinoma (1).
A further 32 diseases each share a sentence with TACC3 in 1 paper.